Y_RNA (Y RNA )
Gene: Miscellaneous RNA gene on chromosome 12 (31,506,303 to 31,506,404, reverse strand). Ensembl gene ENSG00000201228.
Homologues: Orthologues: chimpanzee Y_RNA (97% identical), macaque Y_RNA (93% identical). Paralogues in human: RNY3 (92% identical), Y_RNA (91% identical), Y_RNA (90% identical), RNY3P1 (89% identical), Y_RNA (89% identical), Y_RNA (88% identical), Y_RNA (87% identical), RNY3P16 (86% identical), Y_RNA (86% identical), Y_RNA (85% identical), RNY3P11 (84% identical), RNY3P14 (84% identical), and 97 more.